REV1 (REV1 DNA directed polymerase)
Diseases named in the same sentence as REV1 in open-access papers (continued):
Sharing a sentence is not in itself a finding about the gene and the disease.
infection (18 papers, 2010 to 2025). The state of being infected such as from the introduction of a foreign agent such as serum, vaccine, antigenic substance or organism. "Rev1 infection resulted in approximately 35% pup viability (although individual data ranged from 0 to 75%), while infection with B. melitensis 16M led to complete abortion, in line with the expected attenuation of the vaccine strain." (PMID 38792696, 2024). "Rev1 showed a faint reduction in its counts at 24 h post-infection (PI) followed by an active replication at 48 h PI, but reaching lower levels of infection than those of the virulent strains." (PMID 35335603, 2022). "A similar profile of splenic infection in mice has been observed for another B. ovis attenuated mutant conferring homologous protection in the murine model, and with B. melitensis Rev1, the classical vaccine used against B. ovis infection in sheep." (PMID 32795361, 2020). "It has been reported that Rev1 infection in sheep and rams is fully cleared between the second and third month after subcutaneous or conjunctival vaccination." (PMID 31354728, 2019). "Ten days post infection, viral RNA was isolated from the cell culture supernatants, reverse transcribed, and the rev1-vpu region was sequenced in bulk." (PMID 26554585, 2015). "This method can differentiate field infection with Rev-1 vaccines by producing different band pattern using Pst1 endonuclease enzyme." (PMID 21052561, 2010). "The sixty one positive samples for B. melitensis specific primers were used for RFLP analysis to differentiate Rev-1 vaccine strain from the field strains infection." (PMID 21052561, 2010). "However, attenuation with respect to Rev1 was clearly observed for both tagged vaccines at post-infection weeks 1 and 5 when the experiment was carried out with 108 CFU/mouse, the dose recommended for R vaccines." (PMID 31730501, 2019). "Future studies will address the roles of other factors, such as viral pUL44 or host Rev1, in TLS polymerase repair activity during infection." (PMID 40130902, 2025). "One week post-infection, CFU/spleen values were significantly lower in mice infected with Rev1::Tn7wbdR or Rev1::Tn7wbdRΔwbkC than in those infected with Rev1." (PMID 31730501, 2019). "When similar vaccine doses were compared, RB51WboAKF vaccine at a dose of 1× 106 CFU conferred similar level of immunity as that of strains S19, Rev1 and VTRS1 against B. abortus, B. melitensis and B. suis challenge infection, respectively." (PMID 30856219, 2019). "Thus, by eliminating the primary infection at 28 days in our experimental model, we are not so far away from the conditions of the natural host vaccinated with the reference Rev1 vaccine against Brucella melitensis." (PMID 31354728, 2019).
tumor (18 papers, 2013 to 2025). "In conclusion, REV1 plays different roles in different tumor types, drug susceptibility, and related biological events." (PMID 36246647, 2022). "Currently, there is some evidence that inhibition of TLS polymerase including REV1 not only sensitizes tumor cells to chemotherapeutic drugs, but also reduces the acquisition of drug-induced mutations associated with tumor resistance." (PMID 36246647, 2022). "Minor allele carriers of two REV1 SNPs (rs6761390 and rs3792142) had significantly more often large tumours and tumours with high histological grade and stage than the common homozygotes." (PMID 36246647, 2022). "That means different REV1 SNPs play different roles in different tumor types, drug susceptibility, and related biological events." (PMID 36246647, 2022). "Using short hairpin RNA to inhibit REV1 or REV3 deficient in tumor cells significantly sensitized these tumors to treatment." (PMID 25781640, 2015). "The abnormal expression of REV1 in tumor cells was found to activate the Gly/Ser/Thr metabolic signaling pathways, and the levels of Gly/Ser/Thr were significantly elevated both intra- and extracellularly." (PMID 38802791, 2024). "There is an interaction between ineffective DNA damage repair and metabolic imbalance, which in turn is an important factor affecting tumor radiosensitivity; therefore, REV1 is expected to be a therapeutic target for enhancing tumor radiosensitivity." (PMID 38802791, 2024). "REV1 expression in tumor tissue samples and normal tissue samples from TCGA and TIMER databases were assessed to figure out how REV1 expression differs in particular tumour types." (PMID 36246647, 2022). "REV1 as a potential predictor of drug sensitivity, our study shows that in different tumor types, the expression of REV1 is correlated with the sensitivity of drugs in different mechanisms of pathways." (PMID 36246647, 2022). "And an animal experiment showed that in 27% of the carcinogen-exposed mice, REV1 inhibition completely abolished tumor formation." (PMID 36246647, 2022). "Interfering with TLS using a REV1 inhibitor has been shown to enhance chemotherapy efficacy and suppress tumor growth both in vitro and in vivo." (PMID 35817983, 2022). "We assessed REV1 expression using tumor tissue data and normal tissue data from TCGA and TIMER databases." (PMID 36246647, 2022). "To determine the role of SERTAD2 in REV1-mediated tumor promotion, we carried out a series of rescue experiments." (PMID 35115490, 2022). "Recently, inhibition of the mutagenic translesion synthesis (TLS) protein REV1 was shown to enhance tumor cell response to chemotherapy by triggering senescence hallmarks." (PMID 34771454, 2021). "Overexpression of REV1 accelerates the development of intestinal adenomas in a carcinogen-induced tumor model." (PMID 34663880, 2021). "Reduction of Rev3 or Rev1 in these tumor cells also reduced cisplatin-induced mutagenesis in culture." (PMID 28817566, 2017). "Pertinent to this study, suppression of Rev1 is known to inhibit both cisplatin- and cyclophosphamide-induced mutagenesis, which sensitizes tumors to traditional therapeutics and suppresses the development of tumor chemoresistance." (PMID 38405884, 2024). "Thus, the Rev1BRCT mouse model is useful for interrogating the distinctive roles of Rev1 in the initiation versus the promotion step of tumor development." (PMID 32161626, 2020). "In order to determine whether overexpression of Rev1 would influence spontaneous tumor initiation and progression, we monitored cohorts of Wt and Rev1 Tg mice over their lifespan (> 2 years)." (PMID 32161626, 2020). "Thus, REV1 may be an important biomarker in tumor treatment." (PMID 36246647, 2022).
tumor (continued). "Therefore, the simultaneous inhibition of FANCF and REV1 is a theoretically valid strategy for sensitizing tumor cells to DNA-damaging agents and preventing the development of chemoresistance; however, one concern is that this combination may also lead to toxicity in some normal tissues." (PMID 31511498, 2019). "Therefore aberrant expression of Pol ι, Pol κ, REV1, and possibly other TLS polymerases may promote mutagenesis in tumor cells." (PMID 34663880, 2021). "Hence, targeting REV1 and REV3 might not only increase killing of cancer cells but could also potentially suppress secondary malignancies and tumor relapse." (PMID 28817566, 2017). "Therefore, REV1 may be closely related to radioresistance in tumor cells; however, the role of REV1 and regulatory mechanisms through which it functions in tumor radioresistance have not been elucidated." (PMID 38802791, 2024).
respiratory disorders (1 paper, 2022). "Consequently, we suggest that the role of mutations in REV1 should be investigated more, related to respiratory disorders, in order to better understand its role and to obtain an efficient clinical target." (PMID 36395113, 2022).
REV1 also shares sentences with these, for which no sentence is quoted: B-cell lymphoma (3 papers); colorectal cancer (3); prostate carcinoma (3); adenocarcinoma (2); endometrial carcinoma (2); malignant mesothelioma (2); neutropenia (2); sarcoma (2); urothelial carcinoma (2); uterine corpus endometrial carcinoma (2); acute myeloid leukemia (1); bladder urothelial carcinoma (1); brain tumor (1); cholangiocarcinoma (1); colon adenocarcinoma (1); colorectal tumors (1); dementia (1); emphysema (1); esophageal carcinoma (1); esophagus tumors (1); glioma (1); Granuloma (1); head and neck cancer (1); kidney chromophobe (1); leukopenia (1); lung squamous cell carcinoma (1); myeloma (1); osteosarcoma (1); prostate adenocarcinoma (1); rectum adenocarcinoma (1).
A further 6 diseases each share a sentence with REV1 in 1 paper.